RAPGEF2 (Rap guanine nucleotide exchange factor 2)
Description:
Functions as a guanine nucleotide exchange factor (GEF), which activates Rap and Ras family of small GTPases by exchanging bound GDP for free GTP in a cAMP-dependent manner. Serves as a link between cell surface receptors and Rap/Ras GTPases in intracellular signaling cascades. Also acts as an effector for Rap1 by direct association with Rap1-GTP thereby leading to the amplification of Rap1-mediated signaling. Shows weak activity on HRAS. It is controversial whether RAPGEF2 binds cAMP and cGMP or not. Its binding to ligand-activated beta-1 adrenergic receptor ADRB1 leads to the Ras activation through the G(s)-alpha signaling pathway. Involved in the cAMP-induced Ras and Erk1/2 signaling pathway that leads to sustained inhibition of long term melanogenesis by reducing dendrite extension and melanin synthesis. Also provides inhibitory signals for cell proliferation of melanoma cells and promotes their apoptosis in a cAMP-independent nanner. Regulates cAMP-induced neuritogenesis by mediating the Rap1/B-Raf/ERK signaling through a pathway that is independent on both PKA and RAPGEF3/RAPGEF4. Involved in neuron migration and in the formation of the major forebrain fiber connections forming the corpus callosum, the anterior commissure and the hippocampal commissure during brain development. Involved in neuronal growth factor (NGF)-induced sustained activation of Rap1 at late endosomes and in brain-derived neurotrophic factor (BDNF)-induced axon outgrowth of hippocampal neurons. Plays a role in the regulation of embryonic blood vessel formation and in the establishment of basal junction integrity and endothelial barrier function. May be involved in the regulation of the vascular endothelial growth factor receptor KDR and cadherin CDH5 expression at allantois endothelial cell-cell junctions.
Synonyms: CNrasGEF; nRap GEP; PDZ-GEF1; KIAA0313; NRAPGEP; PDZGEF1; RA-GEF; DKFZP586O1422; RA-GEF-1; RAGEF; Rap-GEP
Tractability: Antibody: its Gene Ontology location is reachable by antibodies, with high confidence; UniProt places it where antibodies can reach, with medium confidence; the Human Protein Atlas places it where antibodies can reach. PROTAC: UniProt records ubiquitination sites on it; ubiquitination databases record sites on it; its protein half-life has been measured.
Gene: Protein-coding gene on chromosome 4 (159,103,013 to 159,360,174, forward strand). Ensembl gene ENSG00000109756.
Subcellular location: Cytoplasm; Cytoplasm, perinuclear region; Cell membrane; Late endosome; Cell junction
Subcellular location (Human Protein Atlas): Cytosol; Plasma membrane
Pathways (Reactome):
Signal Transduction: RAF/MAP kinase cascade
Gene Ontology:
Molecular function: beta-1 adrenergic receptor binding; cAMP binding; cGMP binding; GTPase activator activity; guanyl-nucleotide exchange factor activity; PDZ domain binding; phosphatidic acid binding; protein binding; WW domain binding; calcium ion binding; diacylglycerol binding
Biological process: adenylate cyclase-activating adrenergic receptor signaling pathway; adenylate cyclase-modulating G protein-coupled receptor signaling pathway; cellular response to cAMP; cellular response to cGMP; establishment of endothelial barrier; establishment of endothelial intestinal barrier; G protein-coupled receptor signaling pathway; negative regulation of cell population proliferation; negative regulation of dendrite morphogenesis; neuron projection development; neuropeptide signaling pathway; positive regulation of cAMP-dependent protein kinase activity; positive regulation of dendritic cell apoptotic process; positive regulation of ERK1 and ERK2 cascade; positive regulation of GTPase activity; positive regulation of microvillus assembly; positive regulation of protein kinase activity; Rap protein signal transduction; regulation of cell junction assembly; blood vessel development; brain-derived neurotrophic factor receptor signaling pathway; cellular response to nerve growth factor stimulus; forebrain neuron development; intracellular signal transduction; MAPK cascade; and 14 more
Cellular component: apical plasma membrane; bicellular tight junction; cytoplasm; cytosol; endocytic vesicle; late endosome; membrane; perinuclear region of cytoplasm; plasma membrane; cell-cell junction; neuron projection; neuronal cell body; protein-containing complex; synapse; anchoring junction; postsynapse
Genetic constraint (gnomAD): Loss-of-function variants: 45 observed, 155.58 expected, observed/expected ratio (o/e) 0.29, 90% interval 0.23 to 0.37. The upper end of that interval is the gene's LOEUF score, 0.37, which puts it in group 1 of 6, group 1 being the genes least tolerant of losing a copy. Missense variants: 1,445 observed, 1,947.8 expected, observed/expected ratio (o/e) 0.74, 90% interval 0.71 to 0.77. Synonymous variants: 669 observed, 683.97 expected, observed/expected ratio (o/e) 0.98, 90% interval 0.92 to 1.04.
Homologues: Orthologues: chimpanzee RAPGEF2 (100% identical), macaque RAPGEF2 (99% identical), dog RAPGEF2 (98% identical), rabbit RAPGEF2 (97% identical), rat Rapgef2 (95% identical), pig RAPGEF2 (94% identical), guinea pig Rapgef2 (91% identical), tropical clawed frog rapgef2 (89% identical), mouse Rapgef2 (85% identical), zebrafish rapgef2b (78% identical). Paralogues in human: RAPGEF6 (63% identical), SOS1 (15% identical), SOS2 (15% identical), RAPGEF4 (12% identical), RASGRF1 (12% identical), RASGRF2 (12% identical), RAPGEF3 (11% identical), RAPGEF5 (11% identical), RAPGEF1 (10% identical), RALGDS (10% identical), RASGRP1 (10% identical), RASGRP4 (9% identical), and 12 more.
Diseases named in the same sentence as RAPGEF2 in open-access papers:
RAPGEF2 is named in the same sentence as 25 diseases in open-access papers, as found by Europe PMC text mining. Sharing a sentence is not in itself a finding about the gene and the disease. The quoted sentences say what the papers report.
schizophrenia (8 papers, 2014 to 2024). A major psychotic disorder characterized by abnormalities in the perception or expression of reality. "Abnormal migration of adult-born hippocampal neurons has been described in schizophrenia, and rare inherited copy number variants of RAPGEF2 have been associated with familiar schizophrenia." (PMID 35058752, 2021). "In Rapgef2-cKO mice, the malformation of the commissural system and agenesis of the corpus callosum (CC), were also reported to be associated with schizophrenia-like behavior in mice carrying mutations in the Disrupted in Schizophrenia-1 (DISC-1) gene." (PMID 29747665, 2018). "Moreover, human genetic studies in a cohort of schizophrenia patients showed strong genetic association of rare inherited copy number variations involving RAPGEF2 and RAPGEF6 with schizophrenia." (PMID 29747665, 2018). "Moreover, a chromosomal region containing the RAPGEF2 gene was identified as a rare inherited copy number variant with a linkage to schizophrenia." (PMID 27390776, 2016). "Conditional knockout of either RAPGEF2 or RAPGEF6 in mice caused hyperlocomotion and deficits in learning and memory, which have been likened to symptoms observed in schizophrenia patients." (PMID 38463630, 2024). "Copy number variations in RAPGEF2 and RAPGEF6, which belong to a well conserved PDZ-RAPGEF family, are associated with schizophrenia." (PMID 38463630, 2024). "In human genetic studies of schizophrenia, we uncovered copy-number variants in RAPGEF6 and RAPGEF2 genes." (PMID 26057047, 2015). "In a study investigating the role of miR-19 and RAPGEF2 in schizophrenia using patient-derived hippocampal NPCs (SZ-NPCs), miR-19 was found upregulated in SZ-NPCs, and conservation of the regulation of RAPGEF2 by miR-19 was demonstrated in human embryonic stem cell-derived hippocampal NPCs." (PMID 35058752, 2021). "Therefore, it is of interest to further characterize the physiological functions of the Cdk5-dependent regulation of Rap1 signalling via RapGEF2 and RapGEF6 in psychiatric disorders such as schizophrenia." (PMID 25189171, 2014). "Additionally, RAPGEF2, RAPGEF6, and Rap1 are essential for the development of neural progenitor cells, which has recently been hypothesized as a risk factor for schizophrenia." (PMID 38463630, 2024). "Therefore, we performed the prepulse inhibition test to investigate whether Rapgef2-cKO mice and Rapgef6-KO mice exhibited schizophrenia-like phenotype." (PMID 29747665, 2018). "In conclusion, although there were differences in their brain morphology and the magnitude of the behavioral abnormalities, Rapgef2-cKO mice and Rapgef6-KO mice exhibited hyperlocomotion phenotype and working-memory defect, both of which could be recognized as schizophrenia-like behavior." (PMID 29747665, 2018).
melanoma (5 papers, 2012 to 2024). A malignant, usually aggressive tumor composed of atypical, neoplastic melanocytes. "Pathway identification using the Ingenuity Pathway Analysis software revealed several significant pathways involving regulators of GTPases like Rap1 (SIPA1, a RapGAP protein, and RapGEF2), which pointed toward a significant impact of Rap1 deregulation on melanoma model aggressiveness in vivo." (PMID 22535842, 2012).
epilepsy (2 papers, 2022 to 2025). A brain disorder characterized by episodes of abnormally increased neuronal discharge resulting in transient episodes of sensory or motor neurological dysfunction, or psychic dysfunction. "Another member of the RAPGEF family, RAPGEF2, has been tangentially associated with familial epilepsy in humans and directly in mice with RAPGEF2 knocked out display brain malformations consistent with those seen in human patients with epilepsy." (PMID 35885906, 2022).
Anxiety (1 paper, 2021). Intense feelings of nervousness, tension, or panic often arise in response to interpersonal stresses. "For example, Ntrk3, Tnr, Cacna1h, Clstn2, and Rapgef2 were found to be involved in pathological processes of anxiety." (PMID 33431988, 2021).
autism (1 paper, 2021). Persistent deficits in social interaction and communication and interaction as well as a markedly restricted repertoire of activity and interest as well as repetitive patterns of behavior. "Rare variants in Rapgef2 have also been found in autism patients." (PMID 34064652, 2021).
breast carcinoma (1 paper, 2014). "RAPGEF2 degradation-failure leads to inhibition of hepatocyte growth factor (HGF)-induced cell migration and expression of non-degradable RAPGEF2 suppressed metastasis of human breast cancer cells." (PMID 24904820, 2014).
fibrosarcoma (1 paper, 2022). A malignant mesenchymal fibroblastic neoplasm affecting the soft tissue and bone. "An additional four previously identified genes (RAPGEF2, SLC20A1, CO5A, TIGD2) were also more highly expressed in fibrosarcomas, but the comparison did not exceed the cutoff for significance used in the present study." (PMID 36099287, 2022).
glomerulosclerosis (1 paper, 2025). A hardening of the kidney glomerulus caused by scarring of the blood vessels. "Among these interactions, a nephrin-MAGI-2-RapGEF2-Rap1 signaling axis could be required for continuous SD-FA crosstalk, as podocyte-specific deletion of MAGI-2 or RapGEF2 leads to rapid glomerulosclerosis." (PMID 40457651, 2025).
RASopathy (1 paper, 2017). Developmental syndromes caused by germline mutations (or in rare cases by somatic mosaicism) in genes that alter the Ras subfamily and mitogen-activated protein kinases that control signal transduction. "Primary RASopathy gene SPRED1 is a negative regulator of the pathway; MAP3K2 encodes MEK kinase 2; RAPGEF2 encodes a Ras activator thought to control developmental neuronal migration in the cortex and formation of the corpus callosum." (PMID 28076348, 2017).
tumor (2 papers, 2022 to 2023). "In vivo, the effect of RAPGEF2 on tumor development and the capacity of natural killer (NK) cells to recruit were confirmed." (PMID 35518785, 2022). "To verify the relationship between RAPGEF2 and CD56+ NK cells in HCC, we found knockdown RAPGEF2 in HCC cells reduces tumor infiltrating CD56+ NK cell recruitment in MHCC97 xenograft tumors." (PMID 35518785, 2022). "To investigate the effect of RAPGEF2 on tumor growth, we noticed that silencing RAPGEF2 enhanced tumor growth and raised tumor weight much more than cells expressing Ctrl shRNA." (PMID 35518785, 2022). "To evaluate the relationship between tumor immune microenvironment and the deletion of RAPGEF2, we analyze the different evaluation indicators, like the recruitment of immune cell, TMB, TIDE, and the response for the immunotherapy." (PMID 35518785, 2022). "Meanwhile, we initially analyzed the relationship between RAPGEF2 and tumor immune microenvironment." (PMID 35518785, 2022). "The result revealed that the group of RAPGEF2 deletion has weaker ability to recruit the natural killer (NK) cell and tumor-infiltrating lymphocytes (TILs) than the normal group." (PMID 35518785, 2022). "Additionally, silencing RAPGEF2 accelerated tumor development in the HCC mouse model and decreased CD56+ NK cell recruitment in HCC tissues." (PMID 35518785, 2022). "However, the prognostic value of RAPGEF2 and the relationship between RAPGEF2 and tumor immune microenvironment remain unknown." (PMID 35518785, 2022). "Additionally, deletion of RAPGEF2 plays a critical role in CNV and related to tumor immune microenvironment, whereas the prognostic potential of RAPGEF2 in HCC patient needs to be explored." (PMID 35518785, 2022).
RAPGEF2 also shares sentences with these, for which no sentence is quoted: cancer (2 papers); glioma (2); mental disorder (2); acute myeloid leukemia (1); adult familial myoclonic epilepsies (1); Friedreich ataxia (1); Fuchs endothelial corneal dystrophy (1); generalized epilepsy (1); genetic disorder (1); hepatocellular carcinoma (1); infection (1); malignant glioma (1); medulloblastoma (1); Obesity (1); spinocerebellar ataxia type 37 (1).